MBL2 (mannose binding lectin 2)
Diseases named in the same sentence as MBL2 in open-access papers (continued):
Sharing a sentence is not in itself a finding about the gene and the disease.
chronic gastritis (1 paper, 2017). Inflammation of the stomach that is chronic in nature. "However, the study had two weaknesses in terms of its ability to reach conclusions regarding the role of MBL2 expression in the development of H. pylori-infected chronic gastritis." (PMID 28558668, 2017). "The second weakness is that they could not find any association between MBL2 genotype and the risk of H. pylori-infected chronic gastritis." (PMID 28558668, 2017). "One pediatric study reported that MBL2 mRNA expression in gastric biopsy specimens was higher in H. pylori-positive chronic gastritis than in H. pylori-negative chronic gastritis patients." (PMID 28558668, 2017).
chronic pancreatitis (1 paper, 2010). A chronic inflammatory process causing damage and fibrosis of the pancreatic parenchyma. "Serum MBL2 and MLCK2 measurement might be helpful in discriminating pancreatic adenocarcinoma from chronic pancreatitis and healthy controls." (PMID 20587030, 2010).
chronic viral hepatitis (1 paper, 2017). "The present study investigated the frequencies of rs1800450 (MBL ⁎B, G>A), rs1800451 (MBL ⁎C, G>A), and rs5030737 (MBL ⁎D, C>T) polymorphisms in exon 1 of the MBL2 gene among patients with chronic viral hepatitis." (PMID 28408790, 2017).
complication (1 paper, 2016). Any disease or disorder that occurs during the course of, or because of, another disease, treatment, or procedure. "In multivariate analysis, biliary complications, length of ICU stay after LT, donor MBL2 rs11003125 (G allele, OR = 3.941, P = 0.016) and donor C7 rs6876739 (C allele, OR = 4.608, P = 0.001) were identified as independent risk factors of bacterial infection after LT." (PMID 27063552, 2016).
coronary artery stenosis (1 paper, 2012). "There was an increased frequency of the low MBL2 haplotype group among patients with significant coronary artery stenosis (p = 0.050)." (PMID 22848725, 2012). "Based on the pilot study where associations among variant MBL2 haplotypes, low plasma concentrations of MBL, and increased frequency of significant coronary artery stenosis were demonstrated, increased atherosclerosis is a probable explanation of this finding." (PMID 22848725, 2012).
degenerative arthritis (1 paper, 2020). "The expression of MBL2 was observed in 11 out of 15 cases of AS in the western blot, compared to six in RA, six in gout, and three in degenerative arthritis." (PMID 32518534, 2020).
developmental disabilities (1 paper, 2020). "We did not observe any relationship between the MBL2 genotype and long-term outcomes; however, there was a strong association between a pathological MRI (Barkovich score 3/4) and developmental disabilities." (PMID 33042903, 2020).
dilated cardiomyopathy (1 paper, 2024). Cardiomyopathy which is characterized by dilation and contractile dysfunction of the left and right ventricles. "It has been reported that Mannose-binding lectin 2 (MBL2) gene polymorphisms and expression levels are related to dilated cardiomyopathy (DCM)." (PMID 38167099, 2024).
dysautonomia (1 paper, 2022). An acute or chronic disorder, affecting the sympathetic or parasympathetic nervous system. "We also compared the MBL2 polymorphisms with other severe clinical features like dysautonomia and requirement of mechanical ventilation in patients with GBS." (PMID 35388043, 2022).
empyema (1 paper, 2010). An accumulation of pus in a body cavity, usually the pleural space. "To investigate this further we studied the frequencies of the six functional MBL2 polymorphisms in individuals with thoracic empyema, as well as a control group." (PMID 20078874, 2010). "MBL2 L/H and P/Q polymorphisms in individuals with thoracic empyema and controls." (PMID 20078874, 2010). "None of the MBL2 polymorphisms were individually associated with susceptibility to empyema." (PMID 20078874, 2010).
fibrosis (1 paper, 2020). the formation of excess fibrous connective tissue in an organ or tissue in a reparative or reactive process. "A risk association was observed between polymorphism at the exon 1 MBL2 and periportal fibrosis regression." (PMID 33338108, 2020).
gastritis (1 paper, 2022). Inflammation of the stomach. "The study results showed that TNF-α, IL-1β, IL-6, TLR4, and MBL2 are common among Covid-19, IBD, gastritis, and diarrhea." (PMID 35845309, 2022).
glioblastoma (1 paper, 2013). The most malignant astrocytic tumor (WHO grade IV). "When restricting the analysis to glioblastomas (n = 98), the association was similar for SNP rs1982266 (OR = 1.56, 95% CI = 1.13–2.16, in the dominant model; p-trend using additive model = 0.006), but none of the remaining MBL2 SNPs were individually significantly related to risk." (PMID 23637788, 2013).
heart failure (1 paper, 2016). Inability of the heart to pump blood at an adequate rate to meet tissue metabolic requirements. "MBL2 genotype distribution according to functional classification of heart failure." (PMID 26745156, 2016).
Hodgkins lymphoma (1 paper, 2025). A heterogeneous group of malignant lymphoid neoplasms of B-cell origin characterized histologically by the presence of Hodgkin and Reed-Sternberg (HRS) cells in the vast majority of cases. "Our findings exhibited significant correlations in Hodgkin's lymphoma between CD247, CMTM6, CD25, ENTPD1, MBL2, and CD40." (PMID 40360443, 2025).
hyperthyroidism (1 paper, 2021). Overactivity of the thyroid gland resulting in overproduction of thyroid hormone and increased metabolic rate. "We found CD34 and MBL2 were associated with hyperthyroidism." (PMID 34409035, 2021).
Infertility (1 paper, 2013). "Low-producing MBL2 haplotypes are associated with C. trachomatis serology positive tubal factor infertility patients." (PMID 23781508, 2013). "Depending on the patient definition (i.e., including or excluding C. trachomatis serology), they found that specific MBL2 high producing haplotypes can have a protection of a risk effect in tubal factor infertility." (PMID 23781508, 2013).
intrahepatic cholestasis (1 paper, 2023). A cholestasis characterized by impairment of the bile flow caused by obstruction located in the liver. "Polymorphic variants of CYLD, GC, MBL2, and ZNF572 genes have been collectively associated with the risk of preterm birth or recurrent late pregnancy loss, while dysregulated expression of CYP8B1 may be responsible for pregnancy intrahepatic cholestasis in mice." (PMID 36768581, 2023).
lepromatous leprosy (1 paper, 2020). A chronic communicable infection which is a principal or polar form of leprosy. "Nevertheless, some associations were lost after multivariate logistic correction (FCN1*3C2, FCN2*AGAAGC, and FCN2*GGGCAC with lepromatous leprosy/HBV infection and MBL2*HYPA, MBL2*LYQC, FCN2*GGGCAC with non-lepromatous leprosy/HBV infection) or due to low sample size (MASP1*AC_CTG, FCN3*2B2.2A)." (PMID 33643280, 2020).
myocardial inflammation (1 paper, 2024). "Considering that DCM is associated with factors such as myocardial inflammation, infection and immune responses and that MBL is related to these factors, we hypothesized that MBL2 polymorphisms and circulating MBL levels are associated with the occurrence of DCM." (PMID 38167099, 2024).
Neurodevelopmental delay (1 paper, 2020). "Highest (peak) levels of MBL and MBL2 genotypes were correlated to neuroimaging brain damage or death and long-term neurodevelopmental delay." (PMID 33042903, 2020).
neuropathy (1 paper, 2016). A disorder affecting the nervous system that manifests with pain, tingling, numbness, and/or muscle weakness. "No MBL2-genotype-dependent correlations were observed with proteinuria, retinopathy, neuropathy or cardiovascular events." (PMID 26768002, 2016).
oral diseases (1 paper, 2023). "Background and objective: Some variants in defensin beta 1 (DEFB1) and mannose-binding lectin 2 (MBL2) genes can be associated with oral diseases." (PMID 36832361, 2023).
periodontitis (1 paper, 2020). An acute or chronic inflammatory process that affects the tissues that surround and support the teeth. "So far, a number of studies have evaluated the association between PRRs, SNPs, and periodontitis, including CD14, TLR2, TLR4, and MBL2." (PMID 32831974, 2020).
pertussis (1 paper, 2016). A contagious bacterial respiratory infection caused by Bordetella pertussis. "Single-nucleotide polymorphisms (SNPs) in candidate genes, MBL2, IL17A, TNFα, VDR, and IL10 were genotyped in a unique Dutch cohort of symptomatic clinically confirmed (ex-)pertussis patients and in a Dutch population cohort." (PMID 26894582, 2016). "Allele frequencies and OR for the VDR, TNFα, IL17, MBL2 and IL10 SNPs in the pertussis patient group and control group." (PMID 26894582, 2016). "Genotype frequencies and OR for the VDR, TNFα, IL17, MBL2 and IL10 SNPs in the pertussis patient group and control group." (PMID 26894582, 2016).
polyarthritis (1 paper, 2008). "Previously, Garred and coworkers showed that MBL2 exon 1 variant allele carrier status was associated with early age at onset of RA, which is the adult counterpart of polyarthritis." (PMID 18334024, 2008). "In polyarthritis patients, the presence of low-expressing (deficient) MBL2 genotypes was associated with early age at onset of disease (P = 0.03)." (PMID 18334024, 2008). "MBL2 genotype frequencies were similar in polyarthritis and oligoarthritis patients as compared with control individuals." (PMID 18334024, 2008). "Interestingly, children in the low MBL2 genotype group developed polyarthritis at a younger age than did children in the medium or high genotype groups." (PMID 18334024, 2008). "In the 67 patients with polyarthritis, patients in the low MBL2 genotype group were younger (4.4 years, IQR 3.6 to 7.0 years) at onset of disease than the patients in the medium (10.1 years, IQR 8.4 to 13.0 years) and high (9.5, IQR 5.6 to 13.0 years) genotype groups (P = 0.05)." (PMID 18334024, 2008).
psoriasis (1 paper, 2023). An autoimmune condition characterized by red, well-delineated plaques with silvery scales that are usually on the extensor surfaces and scalp. "Genetic association models for the MBL2 gene rs1800450 SNP with psoriasis risk (total n = 399, controls = 300, psoriasis patients = 99, adjusted by age and sex)." (PMID 38404462, 2023). "The scarcity of previous related studies addressing MBL2 variants and psoriasis was noticed." (PMID 38404462, 2023). "Correlation matrix between psoriasis patients’ demographic data, clinicopathological features, and the MBL2 gene rs1800450 SNP genotyping." (PMID 38404462, 2023).
sarcoidosis (1 paper, 2020). Sarcoidosis is a multisystemic disorder of unknown cause characterized by the formation of immune granulomas in involved organs. "The distribution of MBL2 polymorphisms was similar in the control, ILD-O and sarcoidosis group." (PMID 33101280, 2020).
thyroid disorders (1 paper, 2013). "We present an analysis of the relationship between serum MBL levels/MBL2 genotypes and a number of clinical characteristics in a well-described cohort of pregnant women screened positive for thyroid disorders in the first trimester of pregnancy." (PMID 24339961, 2013).
tongue SCC (1 paper, 2014). "Of the 8 lncRNA, lnc-PPP2R4-5, lnc-SPRR2D-1, lnc-MAN1A2-1, lnc-FAM46A-1, lnc-MBL2-4:1, and lnc-MBL2-4:3 were upregulated in the microdissected tongue SCC tissues." (PMID 25045670, 2014). "Further, changes of lnc-MBL2-4:3 and lnc-AL355149.1-1 expression levels were noticed in the cisplatin-resistant tongue SCC cells." (PMID 25045670, 2014).
tonsillitis (1 paper, 2024). Inflammation of the tonsillar tissue. "Furthermore, complement and coagulation cascades, including MBL2, TFPI, and PROCR have been identified as biomarkers related to phenotypes such as tonsillitis." (PMID 39410993, 2024).
tubal factor infertility (1 paper, 2017). Infertility caused by fallopian tube damage, preventing fertilisation or implantation. "MBL2 polymorphisms have been associated with susceptibility to tubal factor infertility." (PMID 28824344, 2017).
type 2 diabetic nephropathy (1 paper, 2013). "This study is the first study to examine the associations of the MBL2 gene and type 2 diabetic nephropathy." (PMID 24376633, 2013).
vulvovaginitis (1 paper, 2014). An inflammatory pathologic process that affects the vulva and the vagina. "As RVVC is likely polygenic and/or multifactorial, further studies with larger sample sizes are required to confirm the role of MBL2 polymorphisms in association with Candida vulvovaginitis." (PMID 25143944, 2014).
yang deficiency (1 paper, 2022). Yang deficiency is a concept from traditional Chinese medicine. "In addition, we found that MBL2 was significantly upregulated in Qi-yin deficiency patients (upregulated by 2.26-fold) but significantly downregulated in Yang deficiency patients (downregulated to 0.27 compared to healthy control)." (PMID 35087594, 2022). "Considering the different regulated expression levels, ADIPOQ, MBL2, and IGFBP4 might be potential biomarkers for differentiation and identification of Yang deficiency and Qi-yin deficiency syndromes of HF." (PMID 35087594, 2022). "In addition, several disease related proteins were exclusively involved in the PPI network of the Yang deficiency group, such as adiponectin receptor protein 1 (ADIPOQ), mannose-binding protein C (MBL2), and insulin-like growth factor-binding protein 4 (IGFBP4)." (PMID 35087594, 2022). "Furthermore, we found that MBL2 was localized at a hub position in the PPI network; thus we suggest that MBL2 could also be used as a potential biomarker for differentiating Yang deficiency and Qi-yin deficiency syndromes." (PMID 35087594, 2022).
infection (92 papers, 2006 to 2025). The state of being infected such as from the introduction of a foreign agent such as serum, vaccine, antigenic substance or organism. "The study found that polymorphisms in the TLR4 gene (rs4986790), IL-10 gene (rs1800896), TNF-α gene (rs1800629), and MBL2 gene (rs1800450) were significantly associated with patients’ susceptibility to infection, disease severity, and prognosis." (PMID 40692949, 2025). "Key findings include significant associations between polymorphisms in TLR4 (rs4986790), IL-10 (rs1800896), TNF-α (rs1800629), and MBL2 (rs1800450) with infection susceptibility, disease severity, and survival outcomes." (PMID 40692949, 2025). "Five of the included studies investigated the effects of MBL2 variants, focusing on the acquisition of infection and BMI." (PMID 40225935, 2024). "This supports the association of the MBL2 B allele with a lower level of serum MBL following infection by SARS-CoV-2." (PMID 36836739, 2023). "This study confirms an effect of polymorphisms in the MBL2 gene in susceptibility to infection and the humoral IgG response to C. trachomatis infection." (PMID 36012556, 2022). "We observed associations of MBL2 genotype and the stage of infection, and a clue for possible immunological redundancy was observed." (PMID 36012556, 2022). "We confirmed in our previous publication that there is a possible association between MBL2 genotypes with FC infection." (PMID 34567855, 2021). "Deficiency in MBL-2 is associated with increased susceptibility to infection and MBL2 variants have been studied fairly extensively in CF; most have demonstrated an association between low MBL-producing genotypes and more severe lung disease." (PMID 33924524, 2021). "In our previous study, we evaluated the association of the MBL2 gene polymorphism with FC infection in the North Indian population." (PMID 34567855, 2021). "Variations in MBL2 gene are responsible for poor opsonization and are associated with increased susceptibility to various infections, including filarial infection." (PMID 34567855, 2021). "Lower expression of MBL2 leads to higher risk of grade 3 infection from a compromised immune system condition." (PMID 32443732, 2020). "Mutations in the structural and regulatory sequence of the MBL2 gene lead to inter-individual variations in serum MBL levels which have been associated with increased risk of infections." (PMID 31706269, 2019). "Limitations of this study include lack of: control subjects; identification of microorganisms associated with infections; MBL2 genotyping; evaluation of lectin and opsonization pathways; and evaluation of 23-valent pneumococcal vaccination responses." (PMID 31117958, 2019). "In myeloablative, total body irradiation (TBI) -conditioned transplantation-, MBL2 variants have been associated with an increased risk of infection." (PMID 31706269, 2019). "We performed a large-scale study to address the association of genetic polymorphisms in exon 1 of the MBL2 gene with infection risk in European VLBWI." (PMID 28558032, 2017). "Our study, however, found an evident association between MBL2 variants with infection with an odds ratio of 3.55." (PMID 26977272, 2016). "Variations in the MBL2 gene, which induce lowserum protein levels, are associated with the susceptibility to infection and appear toinfluence the development of CAD." (PMID 27982280, 2016). "Nevertheless, it is certain that MBL2 variant alleles are significantly associated with infections in SCD patients from Oman." (PMID 26977272, 2016). "MBL2 is produced in the liver in a response to infection, typically associated with generation of oxidative stress." (PMID 26493216, 2015). "An average of 1.74 (SD = 1.04) episodes of infection occurred in the wild-type MBL2 group, and 2.42 (SD = 1.84) in the variant MBL2 group, with a greater number of infections in the deficient group (at the limit of statistical significance, p = 0.051)." (PMID 24886325, 2014).